CASP1 (caspase 1)
Diseases named in the same sentence as CASP1 in open-access papers (continued):
Sharing a sentence is not in itself a finding about the gene and the disease.
coronary artery disease (3 papers, 2016 to 2024). "Several studies have investigated the role of caspase-1 in the pathogenesis of ischemic heart disease." (PMID 38534442, 2024). "In order to determine the changes of caspase-1 activities in response to the pathogenesis of coronary artery disease, we used the Ingenuity Pathway Analysis (IPA) database." (PMID 27842563, 2016). "The IPA database is one of the most comprehensive omics data analyzing databases available today; we examined the signaling pathways related to extracellular, cytosolic, and nuclear caspase-1 substrates that were upregulated in coronary artery disease." (PMID 27842563, 2016). "Also, our analysis revealed that the upregulated cytosolic caspase-1 substrates in coronary artery disease regulate ER stress." (PMID 27842563, 2016). "Taken together, these analyses suggest that in coronary artery disease, upregulated caspase-1 extracellular substrates are related to inflammatory pathways while upregulated caspase-1 nuclear substrates are more related to pathways that regulate cell death and chromatin regulation." (PMID 27842563, 2016). "Thus, our data suggests potential downstream targets of caspase-1 that may play a significant role in inflammatory disorders such as coronary artery disease." (PMID 27842563, 2016). "Therefore, our findings suggest that caspase-1 and its substrates may play a crucial role during the disease progression of coronary artery disease." (PMID 27842563, 2016). "Interestingly, in the current study, we found that most of caspase-1 substrates are upregulated in coronary artery disease regardless of their subcellular localization." (PMID 27842563, 2016).
cutaneous leishmaniasis (3 papers, 2019 to 2024). Leishmaniasis affecting the skin. "We conducted a case–control study comparing L. guyanensis-cutaneous leishmaniasis (Lg-CL) patients with healthy individuals (HCs) by analyzing the CASP1 genetic variants rs530537A>G, rs531542C>T, rs531604A>T and rs560880G>T." (PMID 39596502, 2024). "In the present study, we investigated caspase-1/IL-1β axis activation in the protective immune response induced by P2Y2 receptor activation in an experimental model of cutaneous leishmaniasis." (PMID 33061823, 2020). "In the present study, we investigated the involvement of the P2Y2 receptor in the activation of NLRP3 inflammasome elements (caspase-1 and 11) and IL-1β secretion during L. amazonensis infection in peritoneal macrophages as well as in a murine model of cutaneous leishmaniasis." (PMID 33061823, 2020).
disc degeneration (3 papers, 2019 to 2022). "The NLRP3/caspase-1/IL-1β axis has been found to be active in human lumbar cartilaginous endplate degeneration and their expression levels are positively associated with the grades of disc degeneration." (PMID 31383789, 2019). "Compared with NPCs from patients with grade IV disc degeneration, the expression of cleaved CASP1, IL-1β and IL-18 was higher in NPCs from patients with grade V disc degeneration." (PMID 32320383, 2020).
emphysema (3 papers, 2011 to 2020). "Mice emphysema, airway inflammation, and oxidative stress were evaluated, the expression of NLRP3, active caspase-1, and active caspase-3 were detected." (PMID 32116706, 2020). "In this study, the NLRP3 inflammasome also played an important part in PM-induced emphysema and airway inflammation in vivo and in vitro with the results that the IL-1β expression, NLRP3, and active caspase-1 (p20) was enhanced in mice and A549 cells after PM exposure." (PMID 32116706, 2020). "Although IL-18 knockout mice exhibit reduced pulmonary inflammation and emphysema compared to wild-type mice after cigarette smoke, pulmonary inflammation occurred independent of NLRP3/caspase-1 axis after four weeks of cigarette smoke exposure." (PMID 28056996, 2017).
encephalitis (3 papers, 2017 to 2021). An acute inflammatory process affecting the brain parenchyma. "This study also confirmed that pyroptosis occurred in mouse brain infections, while it increased in proinflammatory genes and caspase-1 indicated the activation of the inflammasome during pyroptosis, which was closely related to encephalitis." (PMID 34831405, 2021). "CASP-1, IL-1β, and IL-18 were also expressed in the brain of mice with advanced rabies encephalitis (infected intramuscularly), at higher levels compared to the values that we obtained from the mice that had been infected intracranially and euthanized before advanced signs of encephalitis appeared." (PMID 29615985, 2018).
endometrial tumor (3 papers, 2020 to 2025). "In the mouse model, H2 exposure significantly inhibited endometrial tumor growth compared to controls (p < 0.01) and increased expression of NLRP3, caspase-1, and GSDMD, confirming the promotion of pyroptosis." (PMID 41140697, 2025).
enteropathy (3 papers, 2016 to 2019). "In parallel, the enteropathy induced by p31-43 in vivo did not occur in the absence of NLRP3 or caspase 1 and was inhibited by administration of the caspase 1 inhibitor Ac-YVAD-cmk." (PMID 30761127, 2019).
gastric tumors (3 papers, 2020 to 2024). "Immunoblotting demonstrated that Caspase-1 activation levels, measured by detection of the cleavage of pro-Caspase-1 (p45) to its mature form (p20 subunit), were comparable between either gastric tumor or non-tumor tissues from gp130F/F:Nlrp3-/- and gp130F/F mice." (PMID 35299732, 2022). "Furthermore, inflammasome activation levels, determined by immunoblotting and immunohistochemistry for cleaved Caspase-1, which along with ASC is another integral component of inflammasome complexes, were unchanged in gp130F/F and gp130F/F:Nlrp3-/- gastric tumors." (PMID 35299732, 2022).
gastritis (3 papers, 2021 to 2025). Inflammation of the stomach. "In this study, we further addressed Rabeprazole inhibited cell pyroptosis by destroying NLRP3 inflammasome, leading to decrease Caspase-1 activation and IL-1β and IL-18 release, and resulting in alleviating H. pylori-associated gastritis." (PMID 34266494, 2021). "While the expression of pro and mature forms of caspase-1 is increased in 44.4% of infected gastritis patients compared to the control group, the prevalence of this situation in infected ulcer patients is 41.2%." (PMID 40563885, 2025). "H. pylori infection also resulted in upregulated NLRP3 and active caspase-1 expression in both gastritis and ulcer groups." (PMID 40563885, 2025). "When the expression of the pro and active forms of Caspase-1 was examined, H. pylori infection increased the expression in both gastritis and ulcer patients." (PMID 40563885, 2025). "The correlation between expression levels of mature caspase-1 and mature IL-18 was significant in patients with gastritis infected with H. pylori." (PMID 40563885, 2025). "In addition to all these, in 4 infected gastritis patients (22.2% of the population) and 6 infected ulcer patients (35.3% of the population), caspase-1 expression was lower in the pro-form compared to the control group, while the expression level was increased in the active form." (PMID 40563885, 2025). "In patients with gastritis (72.2%) and ulcers (84.6%) infected with H. pylori, concomitance between pro and active forms of caspase-1 is more common than in patients with gastritis (40%) and ulcers (50%) without infection." (PMID 40563885, 2025).
HCMV infection (3 papers, 2017 to 2021). "In summary, our data indicate that the HCMV tegument protein pUL83 binds to cellular AIM2, which partially contributes to the attenuation of the AIM2 inflammasome proteins 24 h post HCMV infection and reduced activation of caspase-1 and IL-1β." (PMID 28219398, 2017). "HCMV infection activates the AIM2/caspase-1/IL-1β pro-inflammatory pathway." (PMID 34372578, 2021). "Lastly, we demonstrate that HCMV infection of HFFs triggers a non-canonical IL-1β activation pathway where caspase-8 promotes IL-1β maturation independently of caspase-1." (PMID 30332797, 2018). "Moreover, they found no changes in caspase-1 cleavage during HCMV infection, which led them to hypothesize that the canonical inflammasome assembly pathway does not play any role during enhanced IL-1β production upon HCMV infection." (PMID 30332797, 2018).
head and neck squamous cell carcinoma (3 papers, 2020 to 2022). A squamous cell carcinoma that arises from any of the following anatomic sites: lip and oral cavity, nasal cavity, paranasal sinuses, pharynx, larynx, and salivary glands. "For example, in pancreatic ductal adenocarcinoma (PDA) and head and neck squamous cell carcinoma (HNSCC), inflammasomes of tumor-associated macrophages activate caspase-1 and mediate the cleavage of GSDMD and the release of mature IL1β, resulting in the suppression of CD8+ T cells." (PMID 36199426, 2022). "Moreover, our previous study showed that CD38 deletion upregulates TLR4 expression, and also, there is a paper reporting that CD38 can induce inflammasome-mediated activation of caspase-1 by activating NLRP3 in head and neck squamous cell carcinoma (HNSCC)." (PMID 33860064, 2021). "In human head and neck squamous cell carcinoma (HNSCC), NLRP3, ASC, CASP1, IL1B and IL18 gene expression is increased as compared to oral mucosa." (PMID 33261061, 2020).
Hypercholesterolemia (3 papers, 2020 to 2024). An increased concentration of cholesterol in the blood. "Additionally, more investigations are needed to elucidate how ox-LDL accumulation decreases SCGN expression and whether the SCGN-regulated NLRP3/Caspase-1 pathway is impaired in patients with hypercholesterolemia." (PMID 39068218, 2024).
hypothyroidism (3 papers, 2021 to 2023). Abnormally low levels of thyroid hormone. "In the present study, we confirmed an increase in caspase-1 levels in the hippocampus of WKY rats with hypothyroidism and found the same effect in the frontal cortex." (PMID 34198731, 2021). "Maternal hypothyroidism increased the gene and protein expressions of NLRP3, Caspase 1, IL-1β, and IL-18 in the deciduae and placentae of rats." (PMID 37047793, 2023). "Interestingly, as in the brain structures in the present model, it has been found that in the heart, hypothyroidism also increases the concentration of caspase-1 protein, which suggests that this action may be one of the important mechanisms of hypothyroidism-induced tissue damage." (PMID 34198731, 2021).
ischemia reperfusion injury (3 papers, 2021 to 2025). Adverse functional, metabolic, or structural changes in ischemic tissues resulting from the restoration of blood flow to the tissue (reperfusion), including swelling; hemorrhage; necrosis; and damage from free radicals. "Studies have shown that silencing caspase-1 can inhibit the activation of the NLRP3/ASC/caspase-1 axis, reducing myocardial functional impairment caused by ischemia-reperfusion injury." (PMID 40672380, 2025).
joint disease (3 papers, 2014 to 2024). "Pyrophosphate and monosodium urate monohydrate (MSUM) crystals responsible for acute and chronic crystal arthropathies were identified as danger signals activating the caspase-1-activating NALP3 inflammasome, inducing pro-IL-1β maturation in macrophages." (PMID 25436167, 2014). "Unlike macrophages or monocytes, NLRP3 mRNA levels, ASC and pro-caspase-1 levels were reduced in neutrophils from RA patients, while the level of active caspase-1 was elevated and positively correlated with the CRP-based 28 joint disease activity score (DAS28-CRP)." (PMID 35095918, 2021).
kidney failure (3 papers, 2017 to 2022). An acute or chronic condition that is characterized by the inability of the kidneys to adequately filter the blood. "Eight genes related to kidney toxicity, including kidney failure (CASP1, FCGR2A, FCGR2B, TLR2, TLR4, P = 0.003), damage of renal tubule (TLR2, TLR4, P = 0.01), proximal tubular toxicity (CTSS, LYZ, SLC22A5, P = 0.007) and their expression across 6 datasets were not confounded by tissue types." (PMID 28051114, 2017).
kidney injury (3 papers, 2018 to 2026). Trauma to the kidney. "Pyroptosis is activated by the NLRP3/caspase-1 axis and has been associated with a large number of kidney injuries and diseases." (PMID 37293812, 2023). "In the present study, we found that administration of Ac-YYAD-cmk, a potent caspase-1-specific inhibitor, prevented cisplatin-induced kidney injury in mice." (PMID 30670928, 2018).
knee osteoarthritis (3 papers, 2021 to 2022). "On the contrary, it has been reported that miR-107 in analogy with miR-107-3p can protect against knee osteoarthritis by downregulating caspase-1 to decrease pyroptosis." (PMID 36569291, 2022).
leprosy (3 papers, 2010 to 2023). Leprosy is a chronic infectious disease affecting primarily the skin and peripheral nervous system. "Analysis on NLRP1 and NLPR3 inflammasomes showed significant correlations between caspase-1 and IL-1β levels in Borderline leprosy, compared to the VV and TT forms of leprosy." (PMID 37887741, 2023). "In our future studies, we will investigate whether susceptibility to mycobacterial infection, such as tuberculosis and leprosy, is increased in the absence of caspase-1 or IL-1β, as would indicate the importance of the inflammasome in host defense against mycobacterial infection." (PMID 20671924, 2010).
liver cirrhosis (3 papers, 2022). "The expression of GSDMD and Caspase-1 was increased in the liver cirrhosis group." (PMID 35634294, 2022). "Immunohistochemical assays showed that NLRP3, GSDMD, caspase-1 and CK19 were more highly expressed in the liver cirrhosis group than in the other groups, and the levels in the medium and high dose Exo-rBMMSC groups were dramatically decreased." (PMID 36552767, 2022). "Mechanistically, NLRP3 inflammasome-activated GSDMD and its pyroptosis were upregulated in liver cirrhosis, while SHED infusion could suppress the expression of GSDMD and Caspase-1, resulting in reduced hepatocyte pyroptosis and inflammatory cytokine IL-1β release." (PMID 35634294, 2022).
liver failure (3 papers, 2019 to 2024). A liver disease characterized by the liver losing or has lost all of its function. "Significantly elevated levels of NLRP3, cleaved caspase-1 and IL-1β and predominant pyroptotic cell death have been observed in the livers of concanavalin (ConA) and D-galactosamine (D-Gal) induced liver failure models." (PMID 31595205, 2019).
malignant mesothelioma (3 papers, 2020 to 2023). A malignant neoplasm of the pleura or peritoneum, arising from mesothelial cells. "Malignant mesothelioma (MM) exhibits decreased level of caspase-1, and doxorubicin induces inflammatory necrosis of MM cells by activating caspase-1." (PMID 37798663, 2023).
mesothelioma (3 papers, 2018 to 2024). A usually malignant and aggressive neoplasm of the mesothelium which is often associated with exposure to asbestos. "Studies have observed a positive correlation between increasing concentrations of cisplatin and doxorubicin and the levels of NLRP3 inflammasome protein and Caspase 1 in human mesothelioma cell line Hmeso, which eventually leads to increased pyroptosis." (PMID 38902235, 2024). "Similarly, it has been shown that in mesothelioma tumors that exhibit attenuated NLRP3 inflammasome activation, doxorubicin and cisplatin activate the NLRP3/caspase-1 signaling pathway to activate pyroptosis and suppress tumor proliferation." (PMID 35883451, 2022). "XMD8-92 inhibited doxorubicin-induced activation of the NLRP3 inflammasome in H2373 mesothelioma cells as depicted by the absence of caspase-1 p20 and IL-1β in the medium after XMD8-92 treatment." (PMID 29416614, 2018).
oral squamous cell carcinoma (3 papers, 2021 to 2024). "In oral squamous cell carcinoma cells, anthocyanin could reduce the viability, inhibit the migration and invasion abilities and enhance the expression of NLRP3, caspase-1 and IL-1β." (PMID 39616223, 2024).
plague (3 papers, 2012 to 2021). Plague is a severe bacterial infection caused by the gram-negative bacterium Yersinia pestis. "Y. pestis has been found to stimulate caspase-1 activation and IL-1β production in MΦs; however, this effect apparently was not dominant early in systemic plague." (PMID 23248776, 2012).
prion disease (3 papers, 2015 to 2024). A transmissible disease that is caused by a protein that is able to induce abnormal folding of normal cellular proteins, leading to characteristic spongiform brain changes, which are associated with neuronal loss without an inflammatory response. "We found that these transcripts are either unchanged (Nlrp3 and Il1b) or only moderately upregulated (Pycard and, to a less extent, Casp1) in the latest stages of prion disease with respect to baseline levels." (PMID 25671600, 2015). "Upregulation of autophagy by inhibiting the activation of caspase-1 may present a novel therapeutic approach to the treatment of prion diseases, simultaneously leading to a reduction of neuroinflammation and accelerating the removal of misfolded proteins." (PMID 29720937, 2018). "Our findings suggest that autophagy up-regulation and inhibition of Caspase-1 may protect against prion-induced neuroinflammation and accelerate misfolded protein degradation and are potential therapeutic approaches for prion diseases." (PMID 29720937, 2018). "Our findings suggest that inhibiting the activation of caspase-1 may hopefully enhance autophagy, and be an effective therapeutic approach for prion diseases." (PMID 29720937, 2018).
retinal disease (3 papers, 2021 to 2025). "Because the essential role of gasdermin in pyroptosis was only recently established in 2015, earlier research on pyroptosis in retinal disease could only aim to identify inflammasome and caspase-1 activation in these diseases." (PMID 35047535, 2021). "Though several methods have been developed to detect inflammasome activation by imaging caspase-1 and other mediators activity in vitro and in vivo, applications to detect NLRP3 inflammasomes in retinal diseases have been limited." (PMID 36703888, 2022). "Importantly, MCMV-infected eyes of MAIDS-10 mice deficient in either caspase-1, GSDMD, or IL-18 all consistently showed a pattern of retinal disease similar, if not identical, to that observed in the present study for MAIDS-10 mice deficient in the NLRP3, NLRP1b, or AIM2 inflammasomes." (PMID 41011779, 2025).
schwannoma (3 papers, 2020 to 2025). A benign, usually encapsulated slow growing tumor composed of Schwann cells. "Injection of an AAV vector, encoding the pro-apoptotic gene (caspase-1) under the P0 promoter in nude mice with the sciatic nerve implanted immortalized human schwannoma cells, induced tumor regression." (PMID 40940747, 2025). "In 2010, HSV-1 amplicon vector-based intratumoral delivery of caspase-1 under the SC promoter was reported to cause regression of schwannoma in a xenograft mouse model." (PMID 40940747, 2025). "Overexpression of caspase-1, following injection of an AAV1 vector encoding caspase-1 under a Schwann-cell specific promoter into schwannoma tumors, led to regression of these tumors with essentially no vector-mediated neuropathology in a murine model." (PMID 32674264, 2020). "Given highly active, EV-mediated communication from SCs, schwannoma can be inhibited by employing genetically modified EVs carrying suicide mRNA/protein or EVs carrying caspase-1 from genetically modified schwannoma cells." (PMID 35455973, 2022).
septic shock (3 papers, 2021 to 2023). Shock caused by infection; frequently caused by gram negative bacteria, although some cases have been caused by other bacteria, viruses, fungi, and protozoa; characterized by fever, chills, tachycardia, tachypnea, and hypotension. "Our study confirmed that septic shock induced myocardial pyroptosis through NLRP3 inflammasome/Caspase-1/GSDMD pathway, and inhibition of pyroptosis was found to alleviate septic shock-induced cardiac dysfunction." (PMID 36992838, 2023).